LPP (LIM domain containing preferred translocation partner in lipoma)
Diseases named in the same sentence as LPP in open-access papers (continued):
Sharing a sentence is not in itself a finding about the gene and the disease.
lung carcinoma (7 papers, 2013 to 2025). "Noticeably, LPP polymorphisms (rs1064607, rs3796283 and rs2378456) were associated with increased susceptibility to lung cancer in males." (PMID 30621612, 2019). "Our results provides evidence for the impact of LPP polymorphisms on the susceptibility to lung cancer in Chinese population." (PMID 30621612, 2019). "Subsequently, haplotype analysis was used to explore the association of LPP gene with lung cancer susceptibility." (PMID 30621612, 2019). "In stratified analyses by gender, three (rs1064607, rs3796283 and rs2378456) of LPP gene were associated with a significantly increased susceptibility for lung cancer among male population." (PMID 30621612, 2019). "Moreover, we previously reported that MMP15, under the control of the transcriptional co-factor LPP, digests N-cadherin in lung cancer cells, and that loss of LPP function caused abnormal stabilization of N-cadherin." (PMID 35174090, 2022). "Conversely, rs2378456 polymorphism in LPP was associated with reduced susceptibility of lung cancer in females under genotype (GC vs GG, OR = 0.37, 95% CI = 0.18–0.76, p = 0.022, power = 1.000) and dominant (GC-CC vs GG, OR = 0.44, 95% CI = 0.23–0.84, p = 0.012, power = 0.998) model." (PMID 30621612, 2019). "In summary, we provided evidence that SNPs in the 3′-UTR region of LPP gene may have an effect on individual susceptibility to lung cancer among Chinese Han individuals, particularly males." (PMID 30621612, 2019). "In this study, we found that three polymorphisms (rs1064607, rs3796283, and rs2378456) in the 3′-UTR of LPP and TNS3 rs9876 polymorphism were significantly associated with susceptibility to lung cancer." (PMID 30621612, 2019). "We genotyped the seven 3′UTR SNPs in NR5A2, LPP, and TNS3 to determine the potential association with the susceptibility to lung cancer." (PMID 30621612, 2019). "We, therefore, propose that These SNPs may affect LPP or TNS3 expression in lung cancer by differential mRNA stability and binding activity of miR-144 and miR-182." (PMID 30621612, 2019). "LPP was overexpressed in lung carcinoma, soft tissue sarcoma, and leukemia." (PMID 27901484, 2017). "In contrast, LPP directly regulates MMP15 to degrade N-cadherin, which results in inhibition of EMT in lung cancer." (PMID 37422473, 2023). "LPP, FOXP1 and NFE2L2 have previously been reported in lung cancer and we have reported the rest of the genes for the first time in lung adenocarcinoma." (PMID 23874428, 2013). "Thus, LPP and TNS3 may have an important role of in the tumorigenesis and progression of lung cancer." (PMID 30621612, 2019). "First, the results of gene-to-environment interactions between LPP gene and lung cancer could not be obtained due to a lack of relevant information." (PMID 30621612, 2019).
lung adenocarcinoma (5 papers, 2013 to 2025). A carcinoma that arises from the lung and is characterized by the presence of malignant glandular epithelial cells. "Loss of LPP function is associated with tumor cell dissemination in mouse orthotopic model of lung adenocarcinoma cell line PC14PE6, pointing to a potential tumor suppressor role." (PMID 41441397, 2025). "LPP was required for TGF-β induced cell migration/adhesion dynamics and regulates the invadopodia formation with SHCA adapter protein cooperation, and loss of LPP/Etv5/MMP-15 may be implicated in the prognostic marker of lung adenocarcinoma." (PMID 33808029, 2021). "LPP rs1064607 polymorphism was significantly correlated with increased risk of lung adenocarcinoma." (PMID 30621612, 2019).
autoimmune disease (4 papers, 2012 to 2024). A disorder resulting from loss of function or tissue destruction of an organ or multiple organs, arising from humoral or cellular immune responses of the individual to their own tissue constituents. "Our study did not detect an association of previously identified autoimmune disease risk SNPs (rs2358817 within VTCN1 gene; rs1049550 within ANXA11 gene; rs6679356 within IL12RB2 gene andrs9865818 within LPP gene) with T1DM in Croatian T1DM trio families." (PMID 23152861, 2012).
type 2 diabetes (4 papers, 2014 to 2016). "LPP gene has shown a robust association with type 2 diabetes in multiple ethnicities as well as combined meta-analysis." (PMID 27168765, 2016). "The LPP locus has been identified as associating with type 2 diabetes susceptibility and obesity, with CpG sites found to be age-associated in a set of seven large extended families." (PMID 27777315, 2016). "The independent variant identified at the LPP locus in our American Indian GWAS for type 2 diabetes was replicated in the additional samples (all American Indian meta-analysis, p = 8.9 × 10−6, OR 1.29 [95% CI 1.15, 1.45])." (PMID 25112377, 2014). "Identification of an independent variant at the LPP locus suggests the existence of more than one type 2 diabetes signal at this locus." (PMID 25112377, 2014). "A trans-ethnic meta-analysis of type 2 diabetes genome-wide association studies has identified seven novel susceptibility variants in or near TMEM154, SSR1/RREB1, FAF1, POU5F1/TCF19, LPP, ARL15 and ABCB9/MPHOSPH9." (PMID 25799151, 2015).
B-cell NHL (3 papers, 2017 to 2020). "A genome-wide association study of 253 Chinese individuals with B-cell NHL also identified a new susceptibility locus between BCL6 and LPP that was significantly associated with the increased risk of B-cell NHL." (PMID 32211398, 2020).
hypothyroidism (3 papers, 2021 to 2024). Abnormally low levels of thyroid hormone. "One of the most intriguing loci selected by lasso from both the hypothyroidism and vitiligo PRS was in the intron of the LPP gene." (PMID 34099659, 2021). "A common genetic etiology was proposed between hypothyroidism and OLP81 and our study supports this, indicating variation at nine loci (IFIH1, LPP, CEP43, TNRC18, C12orf42, TNFSF11, ST3GAL6, IL2RA, and IKZF3) that are strongly associated with both LP and autoimmune hypothyroidism." (PMID 38776927, 2024).
Allergy (2 papers, 2019 to 2020). An allergy is an immune response or reaction to substances that are usually not harmful. "A study group has found that the LPP gene (rs9860547, G‐> A) is a shared susceptibility locus of asthma and self‐reported allergy, with the risk allele being protective against allergy in the meta‐analysis of GWASs, in children and adults with self‐reported allergy and controls." (PMID 33133517, 2020).
Autoimmunity (2 papers, 2016 to 2022). The occurrence of an immune reaction against the organism's own cells or tissues. "Adjusting for non-genetic covariates, GADA loss was associated with low-risk HLA class II genotypes (P = 0.005), and SNPs associated with autoimmunity RELA/11q13 (P = 0.017), LPP/3q28 (P = 0.004), and negatively with IFIH1/2q24 (P = 0.018)." (PMID 36181724, 2022).
breast tumor (2 papers, 2017). "Therefore, we determined if this novel effect of tetracyclines on LPP expression could decrease breast tumor growth." (PMID 28178994, 2017).
colitis (2 papers, 2023 to 2025). Inflammation of the colon. "Finally, we confirmed that the two homologues of LPH from L. rhamnosus (LRP) and L. paracasei (LPP) could also protect mice from colitis." (PMID 37286542, 2023).
gastric cancer (2 papers, 2021 to 2022). A primary or metastatic malignant neoplasm involving the stomach. "In summary, we unveiled that the protumorigenic function of DDX27 was mediated through a cancer-regulating functional axis DDX27/LPP/EMT in gastric cancer." (PMID 35601484, 2022). "These plots suggest Zyxin, LPP, LIMD1, TRIP6, and FBLIM display high levels of mutational frequency in stomach cancer." (PMID 33808029, 2021). "A positive correlation between DDX27 and LPP was observed in the TCGA gastric cancer cohort." (PMID 35601484, 2022). "Here, we elucidated the critical role of DDX27 in gastric cancer progression and found that DDX27 promoted the GC EMT process by regulating the alternative splicing of LPP." (PMID 35601484, 2022). "Here, we investigated the effects and clinical significance of DDX27 in gastric cancer and proved that DDX27 could promote the migratory and invasive ability of GC through the LPP-mediated EMT process." (PMID 35601484, 2022).
acute leukemia (1 paper, 2010). A clonal (malignant) hematopoietic disorder with an acute onset, affecting the bone marrow and the peripheral blood. "mir-616 and mir-28 are derived from transposed elements (LINE, L2 family) and are located within two translocation breakpoints, respectively DDIT3, that is often fused to FUS in myxoid liposarcoma, and LPP, that is fused to MLL in a secondary acute leukemia." (PMID 20567512, 2010).
acute monoblastic leukemia (1 paper, 2005). "In a case of acute monoblastic leukemia, the LPP gene acts as translocation partner of the MLL gene and the tumor expresses MLL/LPP fusion transcripts." (PMID 15649318, 2005).
autoimmune gastritis (1 paper, 2022). Inflammation of the body fundic mucosa of the stomach. "In age-at-onset and diabetes duration adjusted models, RELA/11q13 and FCRL3/1q23 SNPs were associated with IA-2A positivity, LPP/3q28 SNPs were associated with GADA positivity, and IFIH1/2q24 was associated with positivity for autoantibodies related to autoimmune gastritis and thyroid disease." (PMID 36181724, 2022).
autoimmune hypothyroidism (1 paper, 2024). "Five of the most significant hits after HLA—TNFSF11, CEP43, LPP, C12orf42, and IFIH1—and ten overall coincide with the same direction of effect as seen in the FinnGen and/or UKBB autoimmune hypothyroidism GWAS." (PMID 38776927, 2024).
bladder tumors (1 paper, 2023). "Similarly, LPP was expressed at high levels in NAT compared with bladder tumors in the TCGA cohort." (PMID 37422473, 2023).
diabetic retinopathy (1 paper, 2015). "rs201189528 spatially connects with several other loci: SUGP1 (19p13.11), which affects serum lipid levels and dyslipidemia; LPP (3q28), which is associated with T2D in American Indians; and KCNIP3 (2q21.1), which is associated with diabetic retinopathy." (PMID 26191039, 2015).
gallbladder cancer (1 paper, 2024). "A comparative analysis of differential proteomic data revealed 7 hypermethylated or down-regulated genes (e.g., FBN1, LPP, SOD3) and 61 hypomethylated or up-regulated genes (e.g., HBE1, SNRPF, TPD52), which contributed to the early diagnosis of gallbladder cancer." (PMID 38427106, 2024).
Hypertension (1 paper, 2023). The presence of chronic increased pressure in the systemic arterial system. "Moreover, the difference in the myogenic response between the MA segments isolated from the WT and LPP-KO mice was maintained when these were derived from 6-month-old (6 M) animals made hypertensive for 21 days using the deoxycorticosterone acetate (DOCA)-salt model of hypertension." (PMID 37759537, 2023).
inflammatory bowel disease (1 paper, 2025). A spectrum of small and large bowel inflammatory diseases of unknown etiology. "For 6 of these genes, a role in inflammatory bowel disease is supported by other criteria: GWAS associations with nearby SNPs (ANKRD55, LPP, PDLIM7), experimental perturbation (CCDC50, VCAM1), association with measured protein levels (IL6, VCAM1), or drug effects (IL6, VCAM1)." (PMID 40996888, 2025). "Though LPP, which encodes a protein that is localized at sites of cell adhesion, has no obvious specific biological relevance to inflammatory bowel disease, attribution of the nearby GWAS hit to this gene was supported by fine mapping to an intronic SNP." (PMID 40996888, 2025).
Insulin resistance (1 paper, 2012). Increased resistance towards insulin, that is, diminished effectiveness of insulin in reducing blood glucose levels. "Studies suggested that LPP was a substrate of the protein-tyrosine-phosphatase 1 B (PTP1B), which is a negative regulator of insulin signaling pathway and plays important roles in the pathogenesis of insulin resistance." (PMID 23056290, 2012).
Obesity (1 paper, 2016). Accumulation of substantial excess body fat. "Moreover, we have noted that the LPP locus appears to be under positive selection for obesity traits, which may reflect selective pressure from environmental exposure." (PMID 27777315, 2016).
ovarian carcinoma (1 paper, 2024). A malignant neoplasm originating from the surface ovarian epithelium. "In ovarian cancer, a function of LPP and PSAT1 was discovered in endothelial cell motility through focal adhesion and stress fibre production, as well as in cell proliferation and metastasis." (PMID 39309198, 2024).
Paget disease (1 paper, 2024). A malignant neoplasm composed of large cells with large nuclei, prominent nucleoli, and abundant pale cytoplasm (Paget cells). "For example, LPP is implicated in paget disease, DNAJC16 plays a crucial role in coordinating immune responses, and SUGT1 provides resilience against Haemonchus contortus." (PMID 38684985, 2024).
polycystic ovary syndrome (1 paper, 2012). A disorder that manifests as multiple cysts on the ovaries. "Previous genome-wide association study (GWAS) of polycystic ovary syndrome (PCOS) in Han Chinese population has found that SNPs in LPP gene were nominally significant in PCOS patients (P around 10E-05)." (PMID 23056290, 2012).
prostate adenocarcinoma (1 paper, 2022). "Interestingly, expression levels of the ieGenes LPP in prostate adenocarcinoma and EZH2 in thyroid cancer have previously been associated with patient prognosis in cancer, and we observed a similar association within these two cancer types in the TCGA dataset." (PMID 35725412, 2022). "Similarly, the alternate allele for LPP in prostate adenocarcinoma was associated with higher expression of the gene and better outcome (HR = 0.65, CI = 0.45–0.93)." (PMID 35725412, 2022).
skin cancer (1 paper, 2025). "Both studies included in the meta-analysis for LPP found the gene to be associated with skin cancer-related phenotypes, specifically basal cell carcinoma and cutaneous squamous cell carcinoma (OR = 1.114, CI = 1.107–1.121)." (PMID 39923055, 2025). "Therefore, the involvement of LPP in this signalling pathway may suggest a potential connection to skin cancer-related phenotypes (Fig. 4iii)." (PMID 39923055, 2025).
synovitis (1 paper, 2019). Inflammation of a synovial membrane. "Whether the expression level of LPP can represent graded changes in different stages of OA and degree of synovitis and its interaction at sites of focal adhesion in OA FLS merits future investigation and validation in clinical synovial tissues of different OA stage subgroups." (PMID 31523167, 2019).
tumor (26 papers, 2005 to 2025). "While the TENM4 transcript overexpression is also associated with an increase in TENM4 protein in tumor tissue, the relative increase in LPP transcript level in tumor tissue relates to a significant decrease in LPP protein." (PMID 41441397, 2025). "C1 was primarily marked by the expression of genes related to tumor progression and migration (LPP and ATF3)." (PMID 40725006, 2025). "The reminder of the LPP gene is statistically hypomethylated in tumor tissue compared to normal tissue, in both LUAD and LUSC." (PMID 41441397, 2025). "In a B16-OVA melanoma lung metastasis model, the LPP mRNA vaccine led to a significant reduction in tumor nodules, highlighting its potent anti-tumor activity." (PMID 39817564, 2025). "For the gene body of LPP, a significant difference can be seen, suggesting a lower level of methylation in the tumor tissue compared to normal tissue." (PMID 41441397, 2025). "While TENM4 gene also displays a marked increase in expression in LUAD and LUSC, in tumor versus normal tissue, this difference is less obvious for the LPP gene." (PMID 41441397, 2025). "Of the 63 publications on this LIM-domain protein to date, more than half suggest a role for LPP in tumour cell migration, invasion and metastasis." (PMID 37759537, 2023). "Taken together, our results revealed that LPP functioned as a tumor suppressor in BCa and reversed the metastasis-promoting effects of UBE2S." (PMID 37422473, 2023). "Pathologically, LPP is commonly emerged as a critical tumor inducer, accounting for tumor initiation, metastasis, and drug resistance." (PMID 35601484, 2022). "Although LPP has been reported as an oncogene in various tumor malignancies, its role in GC metastasis is not fully confirmed." (PMID 35601484, 2022). "When overexpressed in HIVS-125 cells (human SMC line), LPP enhances migration and cell spreading, and when LPP expression is attenuated, the invasiveness of tumor cells is also decreased." (PMID 34867475, 2021). "Recent evidence has indicated that LPP has become an important inducer of tumor cell migration, invasion, and metastasis." (PMID 33371071, 2020). "LPP has been shown to be a critical inducer of tumor cell migration, invasion and metastasis by virtue of its ability to localize to adhesions and to promote invadopodia formation." (PMID 32211398, 2020). "LPP expression levels in intra-tumor endothelial cells correlate with survival and chemo-resistance in OC patients." (PMID 31652539, 2019). "The levels of LPP in tumor mass of animals treated with CH–siLLP were significantly lower than in controls." (PMID 31652539, 2019). "Herein, we demonstrate that diminished LPP expression reduces circulating tumour cell numbers, impairs cancer cell extravasation and diminishes lung metastasis." (PMID 28436416, 2017). "To determine if reduced LPP expression affected metastasis, we monitored these cohorts following primary tumour resection." (PMID 28436416, 2017). "LPP also plays an important role in tumor metastasis and human epidermal growth factor receptor 2/neu-mediated mammary oncogenesis." (PMID 24278174, 2013). "This might suggest an oncogenic role only for TENM4 while the LPP might function as a tumor suppressor, as suggested by other studies." (PMID 41441397, 2025). "This points out that LPP promoter region is hypomethylated in both normal and tumor tissue." (PMID 41441397, 2025). "The analysis highlighted an increase in TENM4 protein in tumor tissue compared to normal tissue, in accordance with an elevated level of TENM4 transcript, while the level of LPP protein is inversely correlated with the LPP transcript level in tumor versus normal tissue, in both LUAD and LUSC." (PMID 41441397, 2025).